SYNDIG1L (synapse differentiation inducing 1 like)
Synonyms: DSPC1; TMEM90A; capucin; IFITMD4; SynDIG2
Tractability: Antibody: UniProt predicts a signal peptide or a membrane-spanning region.
Gene: Protein-coding gene on chromosome 14 (74,405,894 to 74,426,210, reverse strand). Ensembl gene ENSG00000183379.
Subcellular location: Membrane; Golgi apparatus, cis-Golgi network
Subcellular location (Human Protein Atlas): Cytosol
Gene Ontology:
Cellular component: membrane; Golgi apparatus
Genetic constraint (gnomAD): Loss-of-function variants: 12 observed, 16.52 expected, observed/expected ratio (o/e) 0.73, 90% interval 0.46 to 1.18. The upper end of that interval is the gene's LOEUF score, 1.18, which puts it in group 5 of 6, group 1 being the genes least tolerant of losing a copy. Missense variants: 287 observed, 288.2 expected, observed/expected ratio (o/e) 1, 90% interval 0.9 to 1.1. Synonymous variants: 126 observed, 121.32 expected, observed/expected ratio (o/e) 1.04, 90% interval 0.9 to 1.2.
Homologues: Orthologues: chimpanzee SYNDIG1L (100% identical), macaque SYNDIG1L (98% identical), guinea pig SYNDIG1L (91% identical), rat Syndig1l (89% identical), mouse Syndig1l (89% identical), rabbit SYNDIG1L (89% identical), dog SYNDIG1L (87% identical), pig SYNDIG1L (87% identical), zebrafish syndig1l (55% identical). Paralogues in human: SYNDIG1 (45% identical), TMEM91 (28% identical), PMIS2 (16% identical).
Diseases named in the same sentence as SYNDIG1L in open-access papers:
SYNDIG1L is named in the same sentence as 5 diseases in open-access papers, as found by Europe PMC text mining. Sharing a sentence is not in itself a finding about the gene and the disease. The quoted sentences say what the papers report.
Huntington disease (3 papers, 2012 to 2020). Huntington disease (HD) is a rare neurodegenerative disorder of the central nervous system characterized by unwanted choreatic movements, behavioral and psychiatric disturbances and dementia. "Of them, SYNDIG1L seem to be implicated in Huntington diseases in rodent models, while VRTN has been proposed as a strong candidate of the QTL for vertebral number." (PMID 23638110, 2013). "Virtually nothing is known about the two vertebrate paralogues of SynDIG1, SynDIG1L and TMEM91, although SynDIG1L has been found downregulated in mouse models of Huntington's disease." (PMID 33108974, 2020).
COVID-19 (1 paper, 2024). A disease caused by infection with severe acute respiratory syndrome coronavirus 2. "DAW1, ESF1, KCTD2, USP45, PNMA8A, SYNDIG1L, and CC2D2B are novel genes/proteins that may be linked to COVID-19." (PMID 38674024, 2024).
SYNDIG1L also shares sentences with these, for which no sentence is quoted: congenital heart disease (1 paper); diabetes (1); kidney diseases (1).